TSC1 (TSC complex subunit 1)
Diseases named in the same sentence as TSC1 in open-access papers (continued):
Sharing a sentence is not in itself a finding about the gene and the disease.
tumor (continued). "We have identified SF2, the Drosophila homolog of human SRSF1, as an Achilles heel of pre-tumorous cells devoid of the tumor suppressors Pten or Tsc1, which rely on TORC1 activity to grow and proliferate." (PMID 32599686, 2020). "The increased miR-125b-5p expression in the tumor samples derived from miR-125b-5p-overexpressing Tsc1-/- MEFs was confirmed by qRT-PCR." (PMID 31949495, 2020). "In the second, AMPK activates the tumour suppressor complex that comprises the tuberous sclerosis proteins, Tsc1 and Tsc2 (Tsc1 and Tsc2 function together as a complex are hereafter denoted Tsc1/2)." (PMID 30814334, 2019). "mTOR regulates iNKT1 and iNKT17 differentiation via mTOR complex 1 (mTORC1) and mTORC2 and their tight regulation by the tumor suppressor TSC1 ensures proper iNKT1/17 balance." (PMID 31824499, 2019). "It is caused by mutations in either the TSC1 or TSC2 gene, which result in upregulation of the mammalian target of rapamycin (mTOR) pathway and subsequent tumor growth in various organs such as the brain, heart, skin, eyes, kidney, lung, and liver." (PMID 31039793, 2019). "TSC2 is a tumor suppressor that forms a complex with TSC1 and inactivation of the TSC1/TSC2 complex activates mTORC1 with its specific protein Raptor." (PMID 31244863, 2019). "The tumor suppressor TSC1 is a new co-chaperone of Hsp90 that modulates Hsp90 activity and enhances Hsp90 binding to its inhibitors." (PMID 31645902, 2019). "A second tumor (patient #1) was found to have three disease associated variants: BRAF c.1799 T > A p.(V600E), NF1 c.7079_7082delTTAT p.(F2360Wfs*35), and TSC1 c.2074C > T p.(R692*)." (PMID 31046843, 2019). "We have recently identified the tumor suppressor TSC1 as a novel regulator/co-chaperone of Hsp90 important for the folding and stability of numerous kinase and non-kinase clients including Tsc2 protein (tuberin)." (PMID 31645902, 2019). "The TSC1 and TSC2 genes are located at chromosomes 9q34 and 16p13.3, respectively, and according to Knudson’s tumor suppressor model, it has been established that TSC1 and TSC2 are involved in the development of TSC syndrome." (PMID 30842342, 2019). "Immediately downstream of Akt is the tuberous sclerosis complex (TSC), which consists of the TSC tumor suppressors TSC1 and TSC2, and also Tre2-TBC1D7." (PMID 29515594, 2018). "Wild type TSC1 and 2 combine to form a complex involved in tumor suppression that inactivates the GTPase Rheb, thus decreasing mTOR signaling which relieves mTOR-mediated inhibition of autophagy." (PMID 30443293, 2018). "Loss of TSC1, TSC2, or PTEN leads to hyperactivation of mTOR and therefore the cells and tissues deficient of these tumor suppressors are widely used in the study of mTOR signaling." (PMID 29362480, 2018). "Tuberous sclerosis (TS) is an autosomal dominant condition caused by mutation of either TSC1 or TSC2 and is associated with neurological effects such as seizures, autism and reduced intellect as well as tumor formation in the heart, brain, lungs and kidneys." (PMID 30443293, 2018). "TSC is an autosomal dominant condition caused by mutations in either TSC1 or TSC2 and is characterized by mTORC1 hyperactivity, tumor growth in multiple organs, neurocognitive problems and epilepsy." (PMID 30308940, 2018). "Somatic mutations in TSC1 and TSC2 also contribute to tumor growth via unopposed mTOR signaling, and sporadic AML is similarly characterized by somatic loss-of-function alterations in TSC2." (PMID 30285856, 2018). "Targeted next generation sequencing (NGS) of MTOR, TSC1 and TSC2 genes in the primary tumor, metastasis and blood of the patient, revealed one inactivating TSC2 mutation (c.2739dup; p.K914*) in the tumor cells." (PMID 29764404, 2018). "Although the cells that give rise to tumors in Tsc1-null mice are expected to express nestin, only rare tumor cells preserved this expression, likely because of inactivity of the endogenous (mouse) nestin promoter upon differentiation of tumor cells." (PMID 29184052, 2017).
tumor (continued). "Given the known tumor suppressor role of both TSC1 and PTEN, we used the more restricted MpzCre mouse line to generate suitable single or double mutants, referred to as MpzCre:Tsc1KO, MpzCre:PtenKO, and MpzCre:Tsc1KO:PtenKO." (PMID 28880149, 2017). "The tumour suppressors, Tuberous Sclerosis Complex (TSC)-1 and TSC2, lie upstream of mTORC1 and function together with TBC1D7 to negatively regulate the mTORC1 activator, Ras homolog enriched in brain (Rheb)." (PMID 28415776, 2017). "Five of these CNA-bearing tumours also showed TSC1/TSC2 CN-LOH, and in all cases, a larger fraction of DNA was affected by the CN-LOH event than these CNAs, suggesting they occurred subsequently to a driving LOH event." (PMID 28643795, 2017). "It is suggested that tumor formation is initiated as a consequenceof at least two hits: asTSC1 and TSC2 are tumor suppressor genes, theinactivation of both TSC1 or both TSC2 alleles isnecessary for benign or malignant tumor formation." (PMID 28222202, 2017). "PTEN and TSC1/2 were initially identified as tumor suppressor genes, suggesting that the primordial activation and growth of follicles share some common characters with tumor cells." (PMID 27206316, 2016). "We further examined the NK cell-mediated in vivo rejection of RMA-S cells, an NK-sensitive tumour cell line, and observed that the severe defect in the Tsc1−/− mice was nearly comparable to that in immunocompromised mice." (PMID 27601261, 2016). "Altogether, our integrated analysis demonstrated that 13 of the 16 uRCC tumours with MTOR, TSC1, TSC2 or PTEN mutations exhibited hyperactive mTORC1 signals." (PMID 27713405, 2016). "Tuberous sclerosis complex 1/2 (TSC1/2), a tumor suppressor, acts as a GTPase-activating protein (GAP) for Rheb." (PMID 25738366, 2015). "TSC1 is a potent negative regulator of mTORC1 signaling and is an epithelial tumor suppressor preventing spontaneous PCa development in murine model." (PMID 26318033, 2015). "AMPK monitors and maintains energy homeostasis at the cellular level; because AMPK primarily acts as a component of the LKB1 tumor suppressor cascade upstream of the TSC1/2/mTOR pathway, AMPK is likely to be a tumor suppressor." (PMID 25798539, 2015). "Accumulating evidence indicates that the tuberous sclerosis complex 1 (TSC1), a tumor suppressor that acts by inhibiting mTOR signaling, plays an important role in the immune system." (PMID 26000908, 2015). "It is also interesting to note that upregulation of certain proteins were somewhat counterintuitive, specifically TSC1, TSC2, and PDCD4 as these proteins are typically associated with tumor suppression." (PMID 25999352, 2015). "The expression of TSC1/hamartin was reduced in the tumor tissue in comparison with the surrounding liver tissue." (PMID 26943379, 2015). "TSC1 and TSC2 mutations cause neoplasms in rare disease pulmonary LAM and neuronal pathfinding in hamartoma syndrome TSC." (PMID 25360538, 2014). "Tumor suppressor function of TSC1/TSC2 is exerted by TSC2 that acts as GTPase Activating Protein (GAP) for small GTPase Rheb via its C-terminal domain." (PMID 25360538, 2014). "We present a model whereby the diverse, heterogeneous tumor burden in TSC patients is dependent on when first- and second-hit mutations in TSC1 or TSC2 occur during development and into adulthood." (PMID 25505789, 2014). "It is caused by mutations in either of the two genes, TSC1 or TSC2, which code for the proteins hamartin (chromosome 9q34) and tuberin (chromosome 16p13), respectively, that act as tumour-growth suppressors." (PMID 24884933, 2014). "Speaking to this, it is possible that different tumor types that are prevalent in TSC patients, as well as those that define LAM disease, are derived from TSC1- or TSC2-deficient cells of different neural crest subtypes." (PMID 25505789, 2014).
tumor (continued). "As the TSC1 and 2 complex helps reduce incidence of PTEN nuclear export, and PTEN reduces AKT phosphorylation of the TSC1 and 2 complexes, one can see that the tumor suppressive functions of PTEN are much broader than only its own syndromes." (PMID 28548055, 2013). "Tuberous sclerosis complex 1 (Tsc1) is a tumor suppressor negatively regulating mammalian target of rapamycin complex 1 (mTORC1)." (PMID 23335988, 2013). "Tuberous sclerosis complex (TSC) is an autosomal dominant neurocutaneous syndrome caused by mutation of either TSC1 or TSC2, tumor suppressor genes that encode the proteins TSC1 (hamartin) and TSC2 (tuberin), respectively." (PMID 23355874, 2013). "Previous data showed that inhibition of mTOR by rapamycin up-regulated PDGFR expression in Tsc1−/− and Tsc2−/− cells, and subsequently enhanced PI3K/AKT activation, which reversed the impaired tumor formation by Tsc1−/− and Tsc2−/− cell lines." (PMID 22428038, 2012). "Dysfunction in tumor suppressors TSC1 and 2 and the subsequent upregulation of mTORC1 seems to be a crucial step in the development of this disease." (PMID 22701332, 2012). "The same study also evaluated short-term sirolimus treatment in TSC1 knockout mice, which resulted in evidence of changes in tumor morphology and a reduction in serum VEGF levels." (PMID 23730262, 2012). "It was recently reported that IKKβ increased tumor development and tumor angiogenesis by activating the mTOR signaling pathway through inhibiting tuberous sclerosis 1 (TSC1)." (PMID 22848663, 2012). "TSC1 is an established tumor suppressor gene in UC that exert most of its regulatory function in a complex with TSC2." (PMID 21533174, 2011). "Here, we report that Tuberous Sclerosis Complex 1 (TSC1), a well-established tumor suppressor that regulates cell size, is an important regulator of dE2F1 during development." (PMID 20808898, 2010). "In most tumor cell lines, including Tsc1 null and Tsc2 null MEF cell lines, treatment with rapamycin or RAD001 leads to phosphorylation of AKT at the S473 site, and increased activation." (PMID 19527517, 2009). "Although there is considerable inter-strain variability in tumour development this appears to be more rapid in TSC2 than TSC1 heterozygotes." (PMID 19506736, 2008). "In these models, homozygous TSC1 or TSC2 mutants die at an embryonic stage, whereas heterozygous carriers are predisposed to tumour formation." (PMID 19506736, 2008). "Genetic and biochemical analyses suggest that Rheb functions downstream of the tumour suppressors Tsc1-Tsc2 in the TOR signalling pathway to control growth, and that a major effector of Rheb function is S6K." (PMID 19384426, 2007). "Additionally, dynamic IPA site usage was observed in well-known tumor suppressor genes, including TSC1, HSD17B2, CD58, RUNX1 and INPP4B." (PMID 41218079, 2025). "Notably, TSC1 and TSC2 emerge as the most frequently mutated genes linked to activated mTOR signaling in HCC tumor samples." (PMID 39863613, 2025). "Combination therapy produced intermediate tumor proliferation and CD8+ T cell infiltration, suggesting partial but incomplete reversal of TSC1 deficiency–induced immune evasion, likely constrained by additional immunosuppressive pathways such as IDO1 induction or Treg recruitment." (PMID 41445741, 2025). "Integrating NEU4 and NPL into the TSC1–mTORC1–sialylation axis further refines the mechanistic framework of PD-L1 hypersialylation–driven immune escape, highlighting a coordinated metabolic control of sialic acid turnover in tumor immune regulation." (PMID 41445741, 2025). "While low mTORC1 activity supported localization near tumor cells, hyperactivation of mTORC1 via loss of the negative regulator TSC1 shifted their localization to perivascular regions." (PMID 39567756, 2025).
tumor (continued). "Mutations of the TSC1 and TSC2 genes can affect the mechanistic target of the rapamycin (mTOR) signaling pathway and thus disrupt the regulating mechanisms of cell growth and proliferation, leading to tumor development." (PMID 40723161, 2025). "Collectively, these results indicate that the loss of TSC1 enhances cellular α2,6-sialylation, thereby suppressing apoptosis and promoting tumor cell survival, suggesting that TSC1-mediated regulation of sialylation plays a critical role in malignant progression." (PMID 41445741, 2025). "Mutations in TSC1/TSC2 can lead to mTOR overactivation, promoting tumor growth." (PMID 38731914, 2024). "NF1, TSC1, and TβRII deficiency in TSAE1 tumor cells significantly increased lung nodule counts." (PMID 38997291, 2024). "Because Tsc1 − / − or Tsc2 − / − MEFs have low tumorigenic ability in vivo, we constructed a novel cell line (NTC/T1 null cells) with potent tumorigenicity derived from a subcutaneous tumor formed by the injection of Tsc1 − / − MEFs into nude mice to investigate the in vivo role of ERO1α." (PMID 38610018, 2024). "MiR-130b-enhanced LMS tumor growth and metastasis may therefore enhance tumor growth and metastasis in part via TSC1-dependent mechanisms." (PMID 36701370, 2023). "Moreover, ex vivo analysis of resected lungs from the same mice revealed a 4.7-fold increase in the number of GFP positive tumor foci (P = 0.02) supporting an increase in metastatic capacity following TSC1 knockdown." (PMID 36701370, 2023). "In conclusion, our findings indicate that miR-130b is elevated in LMS, where it may accelerate tumor growth and metastasis through inhibition of the tumor suppressor, TSC1, and promotion of cell migration and invasion." (PMID 36701370, 2023). "We found that LT recipients with HCC exceeding the Milan Criteria could benefit from sirolimus‐based immunosuppression, and the low TSC1/2 expression subgroup (higher tumor activity) benefited the most." (PMID 38045832, 2023). "MiR-130b and the miR-130b/TSC1 axis may therefore provide novel molecular targets for therapeutic intervention to impede tumor growth and metastatic progression of poorly differentiated LMS." (PMID 36701370, 2023). "TSC is characterized by broad phenotypic heterogeneity, suggesting that other events beyond TSC1/TSC2 biallelic loss may act as disease modifiers and susceptibility loci for tumor development." (PMID 36793390, 2022). "Collectively, our data derived from cell lines, syngeneic mouse models, and specimen of patients with NSCLC revealed the prominent significance of TSC1/TSC2 mutations in promoting PD-L1 expression, facilitating T cell infiltration and augmenting tumor immunogenicity." (PMID 35119931, 2022). "It has been suggested that TSC1/TSC2 epigenetic silencing might contribute to tumor formation in TSC and could explain cases where the second hit mutation in TSC1/TSC2 is not found." (PMID 34709498, 2022). "As FNIP1/2 and Tsc1, respectively, have established roles as guardians of these tumor suppressors, it follows that there may be a role for molecular chaperones in mediating FLCN and Tsc2 stability." (PMID 35883484, 2022). "TSC1/TSC2-null fibroblasts are the core tumor cells in TSC FAFs." (PMID 35358092, 2022). "Clustering analysis of BMDCs and MDSC-DCs in the genes of mTOR signaling pathway found that tumor suppressor factors such as Pten, Tsc1, Ddit4, mtor, Rptor, and other genes involved in controlling the activity of rapamycin complex 1 (mTORC1) were found in MDSCs-DCs and are all down-regulated." (PMID 36567953, 2022).
tumor (continued). "Although most TSC tumors are composed largely of tumor cells with complete TSC1/TSC2 loss, TSC FAFs occur in the dermis with nontumor vascular, inflammatory, and other components." (PMID 35358092, 2022). "Loss-of-function TSC1 or TSC2 mutations constitutively switch Rheb to an active GTP-bound state that then aberrantly activates mTORC1, leading to metabolic transformation and uncontrolled tumor growth and encouraging angiogenesis in hypoxic tissues." (PMID 36551683, 2022). "Deleterious mutations in the tumour suppressor genes, Tuberous Sclerosis Complex 1 (TSC1) and TSC2, were also identified which have not been previously reported to our knowledge." (PMID 35201535, 2022). "Whether the co-occurrence between TSC1 mutations and BRAF non-V600E kinase mutations contributes to tumor development is unknown and deserves to be explored in pre-clinical studies." (PMID 35641658, 2022). "As FNIP1/2 and Tsc1 scaffold the tumor suppressors FLCN and Tsc2 to Hsp90, it follows that these co-chaperones may participate in the chaperoning of additional Hsp90-dependent tumor suppressor clients." (PMID 35883484, 2022). "Furthermore, DYRK1A and TSC1 were coexpressed in clinical tumour samples from patients with HCC (Spearman correlation analysis; r = 0.61, p < 9.4e–39; Pearson correlation analysis, r = 0.62, p < 0.0001)." (PMID 35655269, 2022). "As our in vitro studies showed the oncogenic role of miR-130a, we hypothesized that the depletion of miR-130a expression and thereby the restoration of tumor suppressor TSC1 levels in OSCC cells might have an anti-tumor effect in vivo." (PMID 33833339, 2021). "Except for the originally introduced Pten and Tsc1 deletions, no specific mutation was found in more than a single tumor." (PMID 34348664, 2021). "In addition, IKKβ-mediated phosphorylation of TSC1 at S487/S511 leads to TSC1 inhibition and mTORC1 activation, which promotes angiogenesis and tumor development." (PMID 33670113, 2021). "In vivo, TSC1-deficient cells could form SEGA-like tumors and Rapamycin treatment decreased tumor growth." (PMID 33923449, 2021). "TSC is a monogenic disease, and tumor cells with biallelic TSC1 or TSC2 mutations generally do not develop further heritable changes in other genes." (PMID 34806651, 2021). "In our third patient, the primary tumor showed a combination of TSC1, CUL3, DOT1L and SETD2 gene mutations (but not BAP1), whereas the PM had the same genetic mutations plus BAP1 mutation." (PMID 34885018, 2021). "The tumor harbored a heterozygous deletion of 9q34 that contains the TSC1 gene." (PMID 33842348, 2021). "As expected, there was a decrease in miR-130a expression and an increase in TSC1 levels in xenografts treated with antagomiR-130a compared to mock treated ones, which further confirms that the reduced tumor growth in nude mice is due to the targeting of 3′UTR of TSC1 by miR-130a." (PMID 33833339, 2021). "Furthermore, IHC analysis demonstrated that the staining of proliferation maker Ki-67 was much weaker in tumor tissues derived from miR-125b-5p-overexpressing Tsc1-/- MEFs than those in the control counterpart." (PMID 31949495, 2020). "TSC is caused by loss-of-function mutations in the tumor suppressors TSC1 or TSC2, both of which are negative regulators of the mTOR." (PMID 33041976, 2020). "PTCH and TSC1 were proposed to be the critical tumor-suppressor genes in 9q deletions, but this hypothesis is controversial." (PMID 33202923, 2020). "In keeping with these results, loss of specific tumor suppressors, such as promyelocytic leukemia protein (PML) or tuberous sclerosis proteins 1 and 2 (TSC1 and TSC2), has been shown to promote HIF-1α expression through suppression of hypoxia-induced inhibition of mTOR." (PMID 31530290, 2019). "As opposed to the metastatic lesion, next-generation sequencing (NGS) of the primary tumor did not reveal the TSC1 variant." (PMID 31443247, 2019).